GSK3B (glycogen synthase kinase 3 beta)
Diseases named in the same sentence as GSK3B in open-access papers (continued):
Sharing a sentence is not in itself a finding about the gene and the disease.
cardiovascular disease (16 papers, 2016 to 2025). "The inhibition of diabetic EC GSK3β can reduce levels of circulating sVCAM1 and could decrease cardiovascular disease risk and confer long-term cardiovascular protection." (PMID 37762417, 2023). "Furthermore, Snail stabilised by GSK-3β is demonstrated to induce osteogenic EndMT contributing to atherosclerotic calcification in response to the cardiovascular disease risk factor, oxLDL3,41." (PMID 33963183, 2021). "The therapeutic potential of GSK3β inhibitor in the management of cardiovascular diseases is well known, where this molecule modulates the activity of pro-survival signalling pathways and preserves mitochondrial function." (PMID 37626874, 2023). "Glycogen synthase kinase-3 (GSK-3β) is an important mediator of inflammatory response, and GSK-3β activation is associated with multiple cardiovascular diseases." (PMID 36164369, 2022). "In cardiovascular diseases, GSK-3β is involved in the regulation of cardiomyocyte proliferation, cardiac fibrosis, myocardial remodeling, and cardiomyocyte apoptosis." (PMID 34349643, 2021). "GSK-3β is involved in the development of many cardiovascular diseases via multiple signal transduction pathways, such as Wnt/β-catenin, TGF-β1-SMAD-3 and apoptosis." (PMID 34349643, 2021). "Therefore, it is important to better understand the role and regulation of GSK-3β in the pathogenesis of cardiovascular diseases." (PMID 34349643, 2021). "In conclusion, salidroside impairs platelet function, in vivo hemostasis, arterial and venous thrombus formation through inhibition of AKT/GSK3β signaling, suggesting that it may be a novel therapeutic drug for treating thrombotic or cardiovascular diseases." (PMID 32352928, 2020). "In conclusion, salidroside inhibits platelet function and thrombosis via AKT/GSK3β signaling, suggesting that salidroside may be a novel therapeutic drug for treating thrombotic or cardiovascular diseases." (PMID 32352928, 2020). "Thus, significant data implicate GSK3β in the pathogenesis of cardiovascular disease." (PMID 30978208, 2019). "In comparison, GSK3β phosphorylation was analyzed from left ventricular samples of accidental death victims with no history of cardiovascular disease or evidence of cardiovascular disease at autopsy." (PMID 34948382, 2021).
metabolic disorders (16 papers, 2011 to 2025). "In this study, SACe-N-C treatment observably increased the expression of PI3K, Akt and GSK3β, indicating that SACe-N-C intervention alleviates glucose metabolism disorders by regulating the PI3K/AKT/GSK3β signaling pathway." (PMID 39334959, 2024). "Previous studies have demonstrated that RSV decreases anxiety-like behavior by improving increased glycogen synthase kinase-3 (GSK-3β) levels in rats with metabolic disease." (PMID 34621902, 2021). "GSK-3β is involved in glucose metabolism and is dysregulated in metabolic diseases, and the Wnt/β-catenin pathway is activated in metabolic diseases such as diabetes." (PMID 34646830, 2021). "Impaired Akt/GSK-3β signalling pathway has been shown to be involved in the development of metabolic disorders." (PMID 26989696, 2016). "Additionally, the role of GSK3β in metabolic disorders, particularly its interaction with the PI3K/AKT signaling pathway, remains an area for exploration." (PMID 41190025, 2025). "This combination may be particularly beneficial in metabolic diseases, where GSK3β inhibition increases autophagy while AMPK activation reduces inflammation and oxidative stress." (PMID 41190025, 2025). "Furthermore, MG53S255 phosphorylation was mediated by GSK3β (glycogen synthase kinase 3 beta) and markedly elevated in the animal models with metabolic disorders." (PMID 36337049, 2022). "One potential way to improve the efficacy of GSK3β inhibitors in metabolic disease (and potentially prompt future clinical trials) could be to include them in combination therapies." (PMID 27534430, 2016). "To explore the mechanism of metabolic disorder, we evaluated the expression of p‐AKT/AKT and phospho‐glycogen synthase kinase 3 beta (p‐GSK3β)/GSK3β, two important proteins involved in the regulation of glucose metabolism." (PMID 40041941, 2025). "The data suggest that aging subjects develop cardiac abnormalities due to metabolic disorders in numerous metabolites as well as alterations in gene expressions, such as SOS1, CREB, IRS1, GRB2 and GSK3β." (PMID 30669571, 2019). "Cardiac abnormality by PM2.5 exposure might due to metabolic disorder in numerous metabolites as well as alteration in gene expression such as SOS1, CREB and GSK3b." (PMID 30112104, 2018).
brain diseases (12 papers, 2010 to 2026). "DISC1, associated with a variety of brain disorders, activates Wnt/β-catenin signaling by inhibiting glycogen synthase kinase 3 beta (GSK3β) phosphorylation, and promotes neural progenitor cell proliferation." (PMID 31850367, 2019). "GSK-3β has several phosphorylation sites and the phosphorylated tyrosine kinase 216 can increase its activity to hyperphosphorylated tau proteins, which is a hallmark in AD, and the p-tau plays an important role in different brain diseases in which excitotoxicity is implicated." (PMID 31338023, 2019). "The major focus of this review is on the intricate interactions between GSK-3β and neuroregulation, as well as the potential of GSK-3β for the therapeutic intervention of brain disease." (PMID 38107562, 2023). "Due to its involvement in many brain disorders, it has become apparent that normal GSK3β signaling is necessary to maintain brain homeostasis." (PMID 20111716, 2010). "Representative GSK-3β inhibitors and its usage in brain disease models." (PMID 38107562, 2023). "Thus, the roles of GSK3β activity in habituation are of importance for further study to illustrate possible mechanisms of this kinase in brain diseases." (PMID 23658842, 2013). "Thus, GSK-3β is a relevant therapeutic target for the treatment of many brain disorders." (PMID 31191636, 2019). "Thus, the use of EL (preferred to EP) for treatment of brain diseases might be anticipated due to its inhibitory effect on GSK-3β and its pivotal impact at cellular level." (PMID 27579985, 2016). "In light of the critical role of GSK3β in the CNS, several groups have studied the expression pattern and activity of endogenous GSK3β in the brain by immunohistochemistry and light microscopy during brain development, in brain disease processes, and in response to various stimuli." (PMID 20111716, 2010). "It will be of great value to continue exploring the potential coupling of zebrafish AChRs to GSK3β and ERK described in the current study, such that the limitations and opportunities implicit to zebrafish as a model organism for complex brain diseases are fully understood." (PMID 31040768, 2019). "Not surprisingly, the dysregulation of GSK-3β activity may have deleterious consequences leading to brain disorders." (PMID 31191636, 2019). "Further exploring the role of Akt/GSK-3β activation at endosomes could contribute to the development of drugs aimed at specifically modulating GSK-3β, providing new opportunities to treatment of brain diseases." (PMID 30792402, 2019).
bacterial infection (11 papers, 2012 to 2026). "In addition to its effects on barrier function, GSK-3β has been implicated in inflammatory responses to bacterial infection." (PMID 26739349, 2016). "Since its discovery, GSK3β has been shown to be involved in the regulation of many cellular functions including growth, differentiation, embryonic development, cell cycle progression, apoptosis and in the inflammatory response caused by bacterial infection through the regulation of NF-κB activity." (PMID 26200352, 2015). "This suggests that although GSK3β is the isoform generally associated with the inflammatory response to bacterial infections, as reported by several authors, GSK3α may also play an important role in this process through the regulation of pro-inflammatory cytokine expression." (PMID 26200352, 2015). "It is evident that GSK-3β plays a crucial regulatory role in controlling the quality and extent of the cytokine response to a number of bacterial infections in different hosts." (PMID 26664916, 2014). "The protective effects of GSK-3β inhibition were further demonstrated in the live bacterial infection." (PMID 25525303, 2014). "The main objective of this review is to show the importance of GSK3β in innate immunity against bacterial infections through regulation of the inflammatory response induced by virulence factors." (PMID 22691598, 2012). "Using a reverse-phase protein array technology in HeLa, it was reported the SigD-dependent phosphorylation of Akt and its target GSK3β, demonstrating the importance of phosphoinhibition of GSK3β during host cell signaling events through bacterial infection." (PMID 22691598, 2012). "KP was previously reported to function as an inhibitor of GSK3β, which is regarded as a central regulator of the immune response to bacterial infection and is involved in many bacterial-induced inflammatory diseases by regulating the expression of inflammatory mediators." (PMID 40143103, 2025). "We speculated that this balance might be disrupted by the bacterial infection in this study, and the drug treatment decreased GSK3β activation, which led to higher levels of GSK3β phosphorylation." (PMID 40143103, 2025). "Inactivation of GSK3β by Akt-induced phosphorylation may result in activation of transcription factors during bacterial infection, including AP-1, STAT-1, STAT-3, and NF-κB." (PMID 29755479, 2018). "Thus these findings revealed the role of β-catenin/ NF-κB and GSK-3β in modulating the inflammatory response during bacterial infection and also showed that β-catenin acts as a critical regulator of inflammation." (PMID 28430783, 2017). "Furthermore, GSK-3β inhibition effectively protected mice and rats from endotoxin shock or mice from live bacterial infection." (PMID 25525303, 2014). "In addition, while prior studies linked GSK-3β/NRF2 to ferroptosis in noninfected contexts, this study revealed a previously unrecognized role in bacterial infection of the endometrium." (PMID 41413615, 2025).
kidney (10 papers, 2014 to 2025). "This is consistent with previous research indicating that pterocarpan derivatives inhibit oncogenic kinases, including AKT and GSK3B, resulting in cell-cycle arrest and death in breast, prostate, and liver malignancies." (PMID 41516052, 2025). "This was based on our previous finding that IL-10 was critical for the immune regulatory and cytoprotective effect of the Gsk3β pharmacological inhibitor in liver IRI." (PMID 36422999, 2023). "In addition, clinical studies have shown that GSK3β overexpression portends a poor prognosis in patients with ovarian and lung malignancies." (PMID 34023818, 2021). "For example, PELI1 activates the PI3 K/Akt/GSK3β signaling pathway, leading to poor prognosis of patients, and PELI3 promotes colorectal carcinogenesis through TLR4-mediated inflammation." (PMID 40500708, 2025).
neurodevelopmental disorder (10 papers, 2013 to 2024). A behavioral and cognitive disorder with onset during the developmental period that involves impaired or aberrant development of intellectual, motor, or social functions. "Pharmacological inhibition of GSK3β in organoid models of neurodevelopmental disorders has been shown to rescue cellular disease associated phenotypes, highlighting the importance of studying the complex roles of GSK3β to understand and treat disorders of brain development." (PMID 33951093, 2021). "Hence, interruption of GSK3β signaling could impair neurodevelopment, thus lending support to a putative pathogenic role in neurodevelopmental disorders." (PMID 26728762, 2016). "Recent studies have highlighted the significance of protein targets such as heat shock protein 90 (HSP90) and glycogen synthase kinase 3 beta (GSK-3β) in the context of neurodevelopmental disorders, including ADHD." (PMID 39598348, 2024). "Our genetic and biochemical analyses have identified a role for GSK3B in brain development, which could have important aetiological implications for neurodegenerative and neurodevelopmental disorders." (PMID 23951236, 2013). "Notably, it has been shown that activity of GSK3β and ERK1/2 are dysregulated in different neurodevelopmental disorders, including FXS." (PMID 35982038, 2022).
heart disease (6 papers, 2005 to 2025). "We believe that targeting GSK-3β might be a promising target for treating cardiac diseases with more advances in the field and clinical trials." (PMID 34349643, 2021). "The Arrb2/miR-155/GSK3β pathway may be a new mechanism with implications for treatment of heart disease." (PMID 24974728, 2014).
infectious disease (6 papers, 2013 to 2025). A disorder directly resulting from the presence and activity of a microbial, viral, or parasitic agent in humans. "One host protein that is critically involved in the cytokine storm is GSK-3β.GSK-3β is a serine-threonine kinase involved in the inflammatory response to infectious disease and plays a role in the phosphorylation of the SARS-CoV-2 N-protein." (PMID 35444632, 2022). "Glycogen synthase kinase-3β (GSK-3β) is known to regulate inflammatory response in infectious diseases." (PMID 23533310, 2013). "This recommends that GSK3β inhibitors could be repurposed or developed as antiviral agents, particularly in the context of emerging infectious diseases." (PMID 41190025, 2025). "Herbal medicine probably controls the infectious disease mainly based on immunomodulatory agents stimulation (such as GSK3B, MAPK14, PPARγ) will probably help innate and adaptive immune, and regulation the inflammatory cytokines and proinflammatory mediators (like IL-6, IL-8, TNF-α, COX2)." (PMID 29301573, 2018).
immune diseases (5 papers, 2020 to 2024). "GSK3β is a potential target for the treatment of immune diseases." (PMID 33192176, 2020). "Therefore, the inhibitory effect of phospho-GSK3β could trigger a cascade effect on downstream targets and pathways that are involved in inflammation, energy metabolism, and immune dysfunction." (PMID 36676744, 2023). "Therefore, we speculated that GSK-3β could be a possible new target for regulating the differentiation and immunosuppressive function of Bregs in immune diseases." (PMID 33343576, 2020).
adenocarcinoma (4 papers, 2003 to 2023). A common cancer characterized by the presence of malignant glandular cells. "Adenocarcinoma tissue with a reduced level of NLRP12 compared with adjacent tissue exhibited significantly higher β-catenin and p-GSK3β." (PMID 37581937, 2023). "Moreover, correlation analysis of Aqp5 and GSK-3β using Hscore indicated a statistically significant correlation between Aqp5 and GSK-3β in the overall samples and in the subset of IPMN with adenocarcinoma." (PMID 35646902, 2022). "After irradiating 30 NSCLC tissues with 2-Gy X-rays, we found no significant changes in GSK-3β protein expression levels in 12 patient samples (moderately differentiated adenocarcinoma), but p-GSK-3βSer9 and p-GSK-3βTyr216 levels were significantly increased." (PMID 29793508, 2018).
inflammation (4 papers, 2013 to 2025). Aberrant reaction of the microcirculation characterized by movement of fluid and leukocytes from the blood into extravascular tissues. "GSK-3β inhibition correlated with increased IL-10 expression, which may be relevant anti-inflammatory mechanism of this pathway, because IL-10 was reported to have a protective role in colonic inflammation." (PMID 24349609, 2013). "Further experimental results proved that KP reduced the production of proinflammatory cytokines by inhibiting GSK3β/JNK/c-Jun signaling pathways and NF-κB activation, which effectively mitigated the P. aeruginosa-induced acute lung inflammation and injury and elevated the survival rates of mice." (PMID 40143103, 2025). "Given that both brain inflammation and GSK3β activity are known to be influenced by brain 5-HT levels, the current work examined whether low 5-HT impacts the effects of HFD on GSK3β phosphorylation or the mRNA expression of several genes involved in inflammation." (PMID 31920532, 2019).
hematologic malignancies (2 papers, 2017 to 2022). "The specificity of additive effects of 9-ING-41 and the CDK9 inhibitor BAY-1143572 to one cell line, SUDHL-4, is reflective of the complexities of GSK-3β interactions with cell cycling pathways in hematologic malignancies." (PMID 29383130, 2017).
autosomal dominant disease (1 paper, 2025). Autosomal dominant form of disease. "Decades of research indicate that calcium dysregulation is an early driver of AD pathology in both sporadic and autosomal dominant disease, with elevated calcium in the cytosol, rather than stored in the SER, activating calpain-2 to disinhibit GSK3β and cdk5 to hyperphosphorylate tau." (PMID 40365352, 2025).
colonic polyps (1 paper, 2016). "Myricetin treatment reduced the phosphorylated GSK-3β by 86.2% and 74.3%, in small intestinal and colonic polyps (p < 0.01 vs. vehicle control), respectively." (PMID 27507058, 2016). "Myricetin treatment resulted in an increase of active GSK-3β by 245.6% (p < 0.01 vs. vehicle control) and 203.8% (p < 0.01 vs. vehicle control), in small intestinal and colonic polyps, respectively." (PMID 27507058, 2016). "Consequently, the expression of phosphorylated β-catenin at Ser37 was significantly increased in both small intestinal and colonic polyps following modulation of GSK-3β by myricetin (p < 0.01 vs. vehicle control)." (PMID 27507058, 2016).
GSK3B also shares sentences with these, for which no sentence is quoted: hypertrophy (9 papers); multiple sclerosis (8); acute myocardial infarction (7); cognitive disorder (7); gastrointestinal tumor (4); neuroendocrine tumor (4); prediabetes (4); anxiety disorder (3); brain cancer (3); experimental autoimmune encephalomyelitis (3); glomerulopathy (3); metastatic tumor (3); Neurodegeneration (3); neurotoxicity (3); polycystic ovary syndrome (3); Senile plaques (3); central nervous system diseases (2); chordoma (2); Crohn disease (2); delirium (2); Dupuytren Contracture (2); dyslipidaemia (2); encephalitis (2); fibrosarcoma (2); Hepatitis C (2); hyperhomocysteinemia (2); Hypoinsulinemia (2); hypothyroidism (2); invasive ductal carcinoma (2); metastatic colorectal cancer (2).
A further 128 diseases each share a sentence with GSK3B in 2 papers or fewer.